EXOC6B (exocyst complex component 6B)
Description:
Component of the exocyst complex involved in the docking of exocytic vesicles with fusion sites on the plasma membrane.
Synonyms: KIAA0919; SEC15B; SEC15L2; SEMDJL3
Tractability: Antibody: its Gene Ontology location is reachable by antibodies, with medium confidence. PROTAC: ubiquitination databases record sites on it; its protein half-life has been measured.
Gene: Protein-coding gene on chromosome 2 (72,175,984 to 72,826,051, reverse strand). Ensembl gene ENSG00000144036.
Subcellular location (Human Protein Atlas): Nuclear bodies; Nucleoplasm; Cytosol
Gene Ontology:
Molecular function: protein binding
Biological process: exocytosis; Golgi to plasma membrane transport; membrane fission; mitotic cytokinesis; intracellular protein transport
Cellular component: exocyst; plasma membrane
Genetic constraint (gnomAD): Loss-of-function variants: 43 observed, 80.62 expected, observed/expected ratio (o/e) 0.53, 90% interval 0.42 to 0.69. The upper end of that interval is the gene's LOEUF score, 0.69, which puts it in group 2 of 6, group 1 being the genes least tolerant of losing a copy. Missense variants: 618 observed, 783.01 expected, observed/expected ratio (o/e) 0.79, 90% interval 0.74 to 0.84. Synonymous variants: 276 observed, 276.92 expected, observed/expected ratio (o/e) 1, 90% interval 0.9 to 1.1.
Gene-disease validity (ClinGen):
ClinGen rates the evidence that EXOC6B causes each of these diseases.
spondyloepimetaphyseal dysplasia with joint laxity, type 3 (autosomal recessive): Definitive.
Homologues: Orthologues: chimpanzee EXOC6B (99% identical), macaque EXOC6B (99% identical), dog EXOC6B (99% identical), pig EXOC6B (99% identical), rabbit EXOC6B (99% identical), mouse Exoc6b (99% identical), rat Exoc6b (99% identical), guinea pig EXOC6B (98% identical), tropical clawed frog exoc6b (80% identical). Paralogues in human: EXOC6 (71% identical).
Diseases named in the same sentence as EXOC6B in open-access papers:
EXOC6B is named in the same sentence as 21 diseases in open-access papers, as found by Europe PMC text mining. Sharing a sentence is not in itself a finding about the gene and the disease. The quoted sentences say what the papers report.
Intellectual disability (5 papers, 2016 to 2023). "Haploinsufficiency in EXOC6B was considered the likely cause of intellectual disability in this case." (PMID 37085629, 2023). "CORO1A is associated with immunodeficiency 8, ALDOA is associated with glycogen storage disease 12 and ataxia‐telangiectasia‐like disorder 2, and EXOC6B is associated with intellectual disability and developmental delay." (PMID 30307717, 2018). "EXOC6B has also been implicated in the pathogenesis of intellectual disability in four studies." (PMID 37085629, 2023). "One of them also had intellectual disability, but it remains unknown whether the EXOC6B variant was responsible." (PMID 37085629, 2023). "Disruption of EXOC6B was reported in a patient with intellectual disability, epilepsy, and behavioral features resembling autism." (PMID 31861825, 2019).
spondyloepimetaphyseal dysplasia (5 papers, 2022 to 2026). An osteochondrodysplasia that results in abnormalities of bone growth in the vertebral column, epiphysis, and metaphysis. "Spondyloepimetaphyseal dysplasia with joint laxity, type 3 (SEMDJL3; MIM# 618395) is an autosomal recessive genetic skeletal disorder, caused by biallelic pathogenic variants in EXOC6B (MIM# 607880)." (PMID 36150098, 2022). "Biallelic recessive variants in EXOC6B have been associated with spondyloepimetaphyseal dysplasia with joint laxity, type 3, which does not present with visceral organ affection." (PMID 36319675, 2023).
autism spectrum disorder (2 papers, 2023 to 2024). A spectrum of developmental disorders that includes autism, and Asperger syndrome. "Interestingly, both KIRREL3 and EXOC6B genes are also related to autism spectrum disorder (ASD), another cognitive disease with a young age of onset." (PMID 38854406, 2024). "Microdeletions affecting CYP26B1 and EXOC6B were identified in two individuals with brachycephaly, facial asymmetry, abnormal ears, mild joint contractures (elbow/knee) and neurological features (autism spectrum disorder, hyperactivity, and aggressive behaviour)." (PMID 37755482, 2023).
developmental delay (2 papers, 2018 to 2022). "EXOC6B variants have previously been suggested in the genetic etiology of developmental delay." (PMID 36150098, 2022).
spondylo-epi-metaphyseal dysplasia (2 papers, 2022 to 2023). "Pathogenic variants in EXOC6B (Sec15B) have been identified in six patients with spondylo-epi-metaphyseal dysplasias with joint laxity (SEMDJL), a skeletal disorder characterized by spine deformities, severe joint laxity, and multiple joint dislocations." (PMID 37085629, 2023). "Spondylo-epi-metaphyseal dysplasias with joint laxity, type 3 (SEMDJL3) is a genetic skeletal disorder characterized by multiple joint dislocations, caused by biallelic pathogenic variants in the EXOC6B gene." (PMID 36150098, 2022).
ciliopathy (1 paper, 2022). A genetic disorder of the cellular cilia or the cilia anchoring structures, the basal bodies, or of ciliary function. "SEMDJL3 with biallelic pathogenic variants in EXOC6B might represent yet another ciliopathy with central nervous system involvement and joint dislocations." (PMID 36150098, 2022).
dementia (1 paper, 2024). Loss of intellectual abilities interfering with an individual's social and occupational functions. "Again, among their counterpart genotype carriers (KIRREL3 rs4144611 GG + TG or rs580382 TT + CT carriers and EXOC6B rs61619102 GG + GC carriers), there were no such relationships between CD34+CD133+ quartiles and AD or all-cause dementia risk." (PMID 38854406, 2024).
epithelial ovarian cancer (1 paper, 2020). "For example, circRNAs EXOC6B and N4BP2L2 can be used as prognostic biomarkers for epithelial ovarian cancer, and circ_0081001 is a potential marker for the diagnosis of osteosarcoma." (PMID 32378344, 2020).
nephrotic syndrome (1 paper, 2023). A collection of symptoms that include severe edema, proteinuria, and hypoalbuminemia; it is indicative of renal dysfunction. "Mutations in EXOC8 and EXOC2 are associated with neurodevelopmental disorders, and mutations in EXOC6B with skeletal abnormalities and mutations in EXOC4 have been associated with nephrotic syndrome." (PMID 36920342, 2023).
pneumococcal meningitis (1 paper, 2016). An acute purulent infection of the meninges and subarachnoid space caused by Streptococcus pneumoniae, most prevalent in children and adults over the age of 60. "Our strongest signals associated with susceptibility to pneumococcal meningitis were rs139064549 on chromosome 1 in the COL11A1 gene (p = 1.51 × 10−6; G allele OR 3.21 [95% CI 2.05–5.02]) and rs9309464 in the EXOC6B gene on chromosome 2 (p = 6.01 × 10−5; G allele OR 0.66 [95% CI 0.54–0.81])." (PMID 27389768, 2016).
tumor (2 papers, 2016 to 2023). "Previous studies identified EXOC6B as a gene involved in the Notch signaling pathway, a key pathway in tumor progression, though haven’t been validated in OV yet." (PMID 37730669, 2023). "Firstly, the underlying mechanism of the 6 identified PGRs, especially CITED2, EXOC6B, MIA2, and TRPV4, in OV progression and tumor immune microenvironment remained largely unknown, which needs stepwise investigation." (PMID 37730669, 2023).
cancer (1 paper, 2025). A tumor composed of atypical neoplastic, often pleomorphic cells that invade other tissues. "These modules contained several cancer regulators such as Intraflagellar Transport (IFT) complex proteins (IFT74, IFT88), BBSome complex proteins (BBS2, BBS7, BBS9, BBS12), exocyst complex components (EXOC3, EXOC4, EXOC6B, EXOC7, and EXOC8), TTC8, TTC21B, EVC, and NEK1." (PMID 40700427, 2025). "However, TNBC, HER2-enriched and luminal B cancers additionally included exocyst-associated markers (EXOC3, EXOC4, EXOC6B, EXOC7, and EXOC8), which suggested that, unlike luminal A, these cancers not only share dysregulation of ciliogenesis but also dysfunction of transport to cilium." (PMID 40700427, 2025).
EXOC6B also shares sentences with these, for which no sentence is quoted: autism (1 paper); Brachycephaly (1); cognitive disease (1); epilepsy (1); glycogen storage disease (1); Immunodeficiency (1); infectious disease (1); neurodevelopmental disorder (1); osteosarcoma (1).